RALYL (RALY RNA binding protein like)
Synonyms: HNRPCL3
Tractability: PROTAC: ubiquitination databases record sites on it; its protein half-life has been measured.
Gene: Protein-coding gene on chromosome 8 (84,182,787 to 84,921,844, forward strand). Ensembl gene ENSG00000184672.
Subcellular location (Human Protein Atlas): Nucleoplasm
Gene Ontology:
Molecular function: identical protein binding; protein binding; RNA binding; nucleic acid binding
Cellular component: nucleoplasm; nucleus
Genetic constraint (gnomAD): Loss-of-function variants: 9 observed, 14.75 expected, observed/expected ratio (o/e) 0.61, 90% interval 0.37 to 1.07. The upper end of that interval is the gene's LOEUF score, 1.07, which puts it in group 4 of 6, group 1 being the genes least tolerant of losing a copy. Missense variants: 238 observed, 256.81 expected, observed/expected ratio (o/e) 0.93, 90% interval 0.83 to 1.03. Synonymous variants: 84 observed, 92.47 expected, observed/expected ratio (o/e) 0.91, 90% interval 0.76 to 1.09.
Homologues: Orthologues: chimpanzee RALYL (100% identical), macaque RALYL (100% identical), pig RALYL (97% identical), rabbit RALYL (97% identical), guinea pig RALYL (96% identical), mouse Ralyl (96% identical), rat Ralyl (96% identical), zebrafish hnrnpc (47% identical), zebrafish zgc:55733 (47% identical). Paralogues in human: RALY (56% identical), HNRNPC (50% identical), HNRNPCL1 (46% identical), HNRNPCL2 (45% identical), HNRNPCL3 (45% identical), HNRNPCL4 (45% identical).
Diseases named in the same sentence as RALYL in open-access papers:
RALYL is named in the same sentence as 33 diseases in open-access papers, as found by Europe PMC text mining. Sharing a sentence is not in itself a finding about the gene and the disease. The quoted sentences say what the papers report.
hepatocellular carcinoma (5 papers, 2021 to 2025). A malignant tumor that arises from hepatocytes. "Increasing expression of RALYL was observed and acted as an oncogene in hepatocellular carcinoma correlated with stemness." (PMID 40052233, 2025). "Prior work showed that RALYL stabilizes Tgfb2 transcripts in hepatocellular carcinoma, thus increasing the stemness of HCC cells." (PMID 37591832, 2023). "RALYL is a liver progenitor cell-specific gene but its role in hepatocellular carcinoma (HCC) remains unknown." (PMID 33750796, 2021).
CNS cancer (2 papers, 2020 to 2025). "We compared the expression levels of FAIM2, DLGAP2, ATP1B1 and RALYL using ONCOMINE databases and found that these 4 genes were significantly downregulated in brain and CNS cancer compared with the normal group." (PMID 33323543, 2020). "Further investigation revealed that RALYL, a modifier expressed explicitly in malignant cells, may be crucial in driving DMG progression and regulating alternative splicing events, offering a potential therapeutic target for this aggressive glioma subtype." (PMID 40308585, 2025).
colorectal cancer (2 papers, 2022 to 2025). A primary or metastatic malignant neoplasm that affects the colon or rectum. "In addition, these hypermethylated genes, mainly PRDM14, RALYL, ELMOD1, and TMEM132E, were validated and confirmed in colorectal cancer by using publicly available DNA methylation data." (PMID 35065650, 2022). "MeDIP-seq can be used as an optimal approach for analyzing cfDNA methylomes, and 12 probes of four differentially methylated genes identified by MeDIP-seq (PRDM14, RALYL, ELMOD1, and TMEM132E) could serve as potential biomarkers for clinical application in patients with colorectal cancer." (PMID 35065650, 2022).
ovarian clear cell cancer (2 papers, 2021 to 2025). An invasive malignant neoplasm that arises from the ovary and is characterized by a predominance of clear and hobnail malignant epithelial cells. "In another study, overexpression of RALYL suppresses the progression of ovarian clear cell carcinoma by inhibiting MAPK and CDH1 signaling pathways." (PMID 40052233, 2025).
Parkinson disease (2 papers, 2021 to 2024). A progressive degenerative disorder of the central nervous system characterized by loss of dopamine producing neurons in the substantia nigra and the presence of Lewy bodies in the substantia nigra and locus coeruleus. "The microarray expression date showed that RALYL were highly expressed in the normal adrenal, kidney and brain, and low RALYL expression was correlated with mental disorder, Parkinson's disease, and multiple cancers 15-17." (PMID 33437214, 2021). "In humans, RALYL speculatively contributes to brain development and function, with links to neurodegenerative diseases like Alzheimer's and Parkinson's diseases." (PMID 39286762, 2024).
acute kidney injury (1 paper, 2022). Sudden and sustained deterioration of the kidney function characterized by decreased glomerular filtration rate, increased serum creatinine or oliguria. "Six hub genes (MDFI, EHBP1L1, FBXW4, MDM4, RALYL, and ESM1) were identified as potentially predictive of an acute kidney injury." (PMID 36313991, 2022). "The expression of ESM1 and RALYL were markedly increased in control samples, while EHBP1L1, FBXW4, MDFI, and MDM4 were markedly increased in acute kidney injury samples." (PMID 36313991, 2022).
amyotrophic lateral sclerosis (1 paper, 2020). Amyotrophic lateral sclerosis (ALS) is a neurodegenerative disease characterized by progressive muscular paralysis reflecting degeneration of motor neurons in the primary motor cortex, corticospinal tracts, brainstem and spinal cord. "Besides AD and PD, RALYL showed single nucleotide polymorphism in amyotrophic lateral sclerosis (ALS), a neurodegenerative disease, following a genome-wide association study (GWAS)." (PMID 33298176, 2020).
Bardet-Biedl syndrome (1 paper, 2023). A ciliopathy with multisystem involvement. "The gene RALYL, encoding the RNA-Binding Raly-Like Protein and responsible for the cystic Bardet-Biedl Syndrome 1 (BBS), was predominantly expressed in PCs outside the papilla, aligning with the known cortical distribution of cysts in BBS19." (PMID 37468493, 2023).
cervical cancer (1 paper, 2024). A primary or metastatic malignant neoplasm involving the cervix. "Detecting the methylation of the DPP6, RALYL, and GSX1 genes was also used for the early diagnosis of cervical cancer in women in Stockholm, Sweden." (PMID 39766341, 2024).
clear cell carcinoma (1 paper, 2021). "RALYL expression negatively correlated with a poor RCCC prognosis, indicating a potential therapeutic target of RALYL in clear cell carcinoma." (PMID 33437214, 2021).
clear cell renal cell carcinoma (1 paper, 2022). "RALYL has been reported to be downregulated in clear cell renal cell carcinoma, and its reduced expression is associated with poor prognosis, which means that it could serve as a tumor suppressor gene." (PMID 35065650, 2022).
cognitive decline (1 paper, 2020). "Cognitive changes showed a high expression of RALYL accompanied by an apparent slow cognitive decline in the duplicate MMSE tests (first AD diagnostic MMSE and last valid MMSE) during follow-up (multiple t tests, adjusted p = 0.019)." (PMID 33298176, 2020).
colon adenocarcinoma (1 paper, 2025). "Analysis of the UALCAN database further revealed that RALYL undergoes hypermethylation in both colon adenocarcinoma (COAD) and rectum adenocarcinoma (READ), accompanied by a downregulation of its expression in these cancer types." (PMID 40052233, 2025).
dementia (1 paper, 2020). Loss of intellectual abilities interfering with an individual's social and occupational functions. "In MCI and AD dementia, subjects had lower RALYL expression levels compared to NCI in the ROSMAP RNA-seq dataset (multiple one-way ANOVA, adjusted p = 0.022)." (PMID 33298176, 2020).
esophageal squamous cell carcinoma (1 paper, 2023). Esophageal squamous cell carcinoma (ESCC) is a type of esophageal carcinoma (EC) that can affect any part of the esophagus, but is usually located in the upper or middle third. "Moreover, in esophageal squamous cell carcinoma RALYL (RALY RNA Binding Protein-like) is targeted by miR-3912 to hinder transcriptional and post-transcriptional regulatory processes." (PMID 37310937, 2023).
glaucoma (1 paper, 2022). Increased pressure in the eyeball due to obstruction of the outflow of aqueous humor. "BOD1L1, RALYL, LDB3, ACAD10, CDK11A, and DPF3 are also associated with glaucoma topical treatments (P < 1 × 10−5)." (PMID 36450729, 2022).
glioblastoma (1 paper, 2020). The most malignant astrocytic tumor (WHO grade IV). "We analyzed the FAIM2, DLGAP2, ATP1B1 and RALYL alterations using the cBioPortal online tool for Glioblastoma Multiforme (TCGA, Firehose Legacy)." (PMID 33323543, 2020).
lung carcinoma (1 paper, 2024). "RALYL instead is known to increase resistance to cisplatin in HCC, and we surmise that this mechanism is not used in Lung cancer." (PMID 38443409, 2024).
lymph node metastasis (1 paper, 2021). "Correlation analysis was conducted to evaluate the relationship between RALYL expression and the clinical characteristics of OCCC, including age, pathological differentiation, tumor depth, lymph node metastasis, distant metastasis, and tumor stage." (PMID 33437214, 2021).
metastatic tumors (1 paper, 2015). "Like-wise we observed a robust increase in RALYL and FOXP2 expression in metastatic tumors compared to the non-metastatic primary xenograft." (PMID 26159519, 2015).
neuroblastoma (1 paper, 2015). Neuroblastoma (NB) is the most common solid, extracranial childhood tumor. "Tissue microarray analysis coupled with automated IHC revealed significant association of RALYL to the tumor grade in a cohort of 25 neuroblastoma patients." (PMID 26159519, 2015). "Kaplan-Meier plots showed a significant association between increased expression of CFHR3, MDFIC, CSMD3, FOXP2, or RALYL (genes with gains in coding regions) and poor OS in patients with neuroblastoma." (PMID 26159519, 2015). "RALYL IHC revealed nuclear positivity with variable levels the human neuroblastoma tissue cores analyzed." (PMID 26159519, 2015).
ovarian carcinoma (1 paper, 2021). A malignant neoplasm originating from the surface ovarian epithelium. "RALYL expression was obvious down-regulated in both ovarian cancer cell lines when compared to the normal ovarian cell line." (PMID 33437214, 2021).
cancer (7 papers, 2015 to 2025). A tumor composed of atypical neoplastic, often pleomorphic cells that invade other tissues. "As far as P38 pathway activation in cancer is concerned, in our study, RALYL, HNRNPC, and p38 were investigated, and the results indicated that HNRNPC and p38 are associated with the role of RALYL in CRC." (PMID 40052233, 2025). "Previous studies have shown that RALYL promotes the stemness maintenance of cancer stem cells, and our analysis further revealed its association with poor prognosis in DMG." (PMID 40308585, 2025). "Next, the effects of RALYL on cancer stemness were investigated by both in vitro and in vivo assays." (PMID 33750796, 2021). "In the present study, RALYL played a role in cancer inhibition through HNRNPC, which may be consistent with previous studies that HNRNPC promotes CRC progression involved in tumor growth." (PMID 40052233, 2025). "Consequently, the targets of STAT3, including NANOG, c-Jun, c-Myc, and BCL-XL, which played important roles in stemness of cancer, were also upregulated in RALYL-overexpressing cells." (PMID 33750796, 2021). "Therefore, RALYL may bind to HNRNPC to affect its structure to play a role in cancer inhibition." (PMID 40052233, 2025). "According to the data, numerous genes (such as H2AFX, CDKN2A, TTF2, IKBKE, and UBE2I) were markedly upregulated in many cancer types, while some genes (such as ARRB1, LMO3, KHDRBS2, CIRBP, and RALYL) were remarkably downregulated in multiple cancer types." (PMID 35003212, 2021). "MRPL38, EMILIN3 and RALYL are overexpressed in non-resistant cancer cell lines." (PMID 38443409, 2024).
tumor (7 papers, 2015 to 2025). "MNK2 alternative splicing is essential for the tumor suppressive role of RALYL, along with RALYL regulating MNK2 alternative splicing via HNRNPC in CRC." (PMID 40052233, 2025). "Analysis of data from TCGA using UALCAN and GEPIA showed that RALYL expression was low in primary tumor in COAD and READ compared with normal tissue." (PMID 40052233, 2025). "This activation of the p38 MAPK signaling pathway leads to suppressed tumor proliferation, highlighting RALYL's potential as a therapeutic target for CRC." (PMID 40052233, 2025). "It was worth noting in the results of immunohistochemical staining that RALYL expression was negatively correlated with Ki67 expression in tumor tissue, which was consistent with that in human CRC tissue." (PMID 40052233, 2025). "The effect of RALYL on tumor invasion and metastasis was characterized by cell migration, invasion, and in vivo liver metastasis assays." (PMID 33750796, 2021). "Correlating the RALYL positivity to the tumor grade clearly identified the directly proportional tumor-grade → RALYL expression association." (PMID 26159519, 2015). "RALYL positivity was relatively low in Grade 1, while its expression increased per increased tumor invasive potential, with maximal gain in highly invasive tumors." (PMID 26159519, 2015). "This suggests that RALYL may serve as a tumor-specific RNA-modifying protein in DMG, potentially playing a critical role in disease progression." (PMID 40308585, 2025). "Overexpression of RALYL suppresses cell proliferation in vitro and tumor growth in vivo in CRC." (PMID 40052233, 2025). "Overexpression of RALYL inhibited cell proliferation and tumor growth in CRC both in vitro and in vivo, suggesting that RALYL may function as a tumor suppressor gene in CRC." (PMID 40052233, 2025). "Overexpression of RALYL suppressed CRC tumor growth in mice." (PMID 40052233, 2025). "Results of our study indicated that MNK2 alternative splicing is essential for the tumor suppressive role of RALYL so that RALYL may inhibit CRC through regulating MNK2 alternative splicing by increasing MNK2a and decreasing MNK2b." (PMID 40052233, 2025). "Generally, RALYL played an anti-tumor role in OCCC, and might sever as a therapeutic and prognostic biomarker for OCCC." (PMID 33437214, 2021). "In addition, over-expression of RALYL showed an obvious anti-tumor effect by inhibiting MAPK and CDH1 signaling pathways." (PMID 33437214, 2021). "Interestingly, we found that the RALYL-expressing cells were significantly enriched in PLC-8024-induced tumor tissues treated with chemotherapeutic reagents, indicating that they are more chemoresistant." (PMID 33750796, 2021). "Furthermore, the frequency of tumor formation was decreased in cells with RALYL silencing (1/6 in Huh7 and 3/5 in Hep3B), compared with scrambled shRNA-transfected cells (6/6 in Huh7 and 5/5 in Hep3B)." (PMID 33750796, 2021). "A STAT3-specific inhibitor, NSC74859, could decrease HCC cells with high RALYL expression in cell proliferation and tumor growth." (PMID 33750796, 2021). "XTT proliferation assays showed that the overexpression of RALYL promoted tumor cell proliferation." (PMID 33750796, 2021). "Furthermore, given its selective expression in malignant tumor components, RALYL-based therapeutic approaches—such as targeted therapy, tumor vaccines, or CAR-T cell therapy—could offer potential clinical applications." (PMID 40308585, 2025). "In addition to the factors mentioned, it is likely that other SFs identified here as having consistent changes across all tumor types (SNRPB, RNPS1, RBM34, ELAVL1, and RALYL) could contribute to tumor-associated splicing events in the analyzed datasets." (PMID 33621242, 2021). "In contrast to control cells, RALYL-overexpressing cells showed higher foci formation frequencies and colony formation capacity in soft agar, indicating that RALYL could significantly enhance tumor cell growth in both anchorage-dependent and anchorage-independent manners." (PMID 33750796, 2021).
tumor (continued). "RALYL might also play the anti-tumor effects by suppressing these oncogenic genes." (PMID 33437214, 2021). "RALYL binds to HNRNPC to promote MNK2 splicing into MNK2a instead of MNK2b, consequently activating the p38 MAPK signaling pathway and inhibiting tumor proliferation in CRC." (PMID 40052233, 2025). "It was confirmed by IHC assay that RALYL expression was lower in the tumor than in adjacent normal tissue, which was negative with the expression of Ki67, a cell proliferation‐related marker." (PMID 40052233, 2025). "Notably, we identified RALYL as a key gene significantly correlated with poor prognosis in DMG, potentially contributing to tumor stemness and proliferation." (PMID 40308585, 2025). "However, when analyzing expression across distinct cellular subpopulations, we found that RALYL displayed higher expression in malignant fractions, particularly in AC-like, NPC-like, and OPC-like tumor cells, while being minimally expressed in normal cells." (PMID 40308585, 2025). "Results of human CRC samples assay for mRNA and protein demonstrated that RALYL was downregulated in tumor tissue compared with adjacent normal tissue." (PMID 40052233, 2025). "Specifically, RALYL binds to HNRNPC to promote the splicing of MNK2 into MNK2a instead of MNK2b, which consequently activates the p38 MAPK signaling pathway and inhibits tumor proliferation in CRC." (PMID 40052233, 2025). "In clinical analysis, RALYL expression had a strong negative correlation with the tumor depth and stage, and the patients with high RALYL expression demonstrated a better prognosis." (PMID 33437214, 2021). "Third, the in vivo tumor formation experiment revealed that as few as 50,000 RALYL-overexpressing cells were sufficient to generate tumors in nude mice, whereas no tumor was formed when mice were injected with the same amount of control cells." (PMID 33750796, 2021). "The results showed that RALYL expression had a strong negative correlation with the tumor depth and stage (P<0.05)." (PMID 33437214, 2021).
neurodegenerative disease (2 papers, 2020 to 2024). A disorder of the central nervous system characterized by gradual and progressive loss of neural tissue and neurologic function. "A few studies have, however, documented the potential role of RALYL in neurodegenerative disease." (PMID 33298176, 2020).
RALYL also shares sentences with these, for which no sentence is quoted: Alzheimer disease (1 paper); brain tumors (1); Cirrhosis (1); COVID-19 (1); glioma (1); mental disorder (1); Obesity (1); small cell lung carcinoma (1).